ADAM8 (ADAM metallopeptidase domain 8)
Diseases named in the same sentence as ADAM8 in open-access papers (continued):
Sharing a sentence is not in itself a finding about the gene and the disease.
leukopenia (2 papers, 2017 to 2022). "ADAM8 deficiency associated leukopenia affected almost all major leukocyte (sub)populations." (PMID 28916789, 2017). "Adam8–/– and WT mice developed leukopenia 12 hours after P. aeruginosa infection, but neutrophil counts in the blood of Adam8–/– mice were increased compared with WT animals, potentially a result of reduced neutrophil transmigration." (PMID 35132956, 2022). "In contrast to hematopoietic ADAM8 deficient mice, no leukopenia was observed and whole-body ADAM8 deficiency even resulted in slightly increased T cell and NK cell counts under hyperlipidemic conditions." (PMID 28916789, 2017). "Although ADAM8 might indirectly affect both processes, via these two substrates, the fact that whole-body ADAM8 deficient mice failed to display leukopenia does not plead for this notion." (PMID 28916789, 2017).
melanoma (2 papers, 2021 to 2022). A malignant, usually aggressive tumor composed of atypical, neoplastic melanocytes. "In addition, the release of ADAM10 in EVs by melanoma cells was shown to be linked to a paxillin/integrin interaction and a subsequent shift to lipid rafts, supporting the suggested mechanism for ADAM8 exosomal release." (PMID 35216088, 2022).
ovarian carcinoma (2 papers, 2022). A malignant neoplasm originating from the surface ovarian epithelium. "We found that after the binding of uPAR and ADAM8, the active form of ADAM8 (90 kDa) was produced, which promoted ovarian cancer metastasis." (PMID 36231102, 2022). "The volcano plot shows that nine DEGs were upregulated in ovarian cancer, with ADAM8 the most significantly upregulated in ovarian cancer (p = 4.94 × 10−9)." (PMID 36231102, 2022). "In addition, ALG3 was found to increase the α1,3-mannosylation of uPAR and enhance its interaction with and activation of ADAM8, thus promoting ovarian cancer metastasis." (PMID 36231102, 2022). "Our study demonstrated that reducing uPAR α1,3-mannosylation by uPAR MUT cDNA inhibited the binding of uPAR to ADAM8, which reduced active ADAM8 and thus the downstream Ras/ERK signaling pathway mediating ovarian cancer metastasis." (PMID 36231102, 2022). "In the peritoneal adhesion assay, we also proved that uPAR cDNA promoted ovarian cancer adherence to HPMCs, but uPAR MUT cDNA and anti-ADAM8 decreased peritoneal metastasis." (PMID 36231102, 2022).
rheumatoid arthritis (2 papers, 2011 to 2017). A chronic, systemic autoimmune disorder characterized by inflammation in the synovial membranes and articular surfaces. "ADAM8 expression is increased in the interface tissue around a loosened hip prosthesis and in the pannus and synovium of patients with rheumatoid arthritis, but its potential role in these processes is unclear." (PMID 20683884, 2011).
systemic sclerosis (2 papers, 2022 to 2024). A chronic disorder, possibly autoimmune, marked by excessive production of collagen which results in hardening and thickening of body tissues. "Using ultrasound, they found, compared to control, stretching reduced skin thickness, increased subcutaneous tissue mobility, and downregulated genes related to systemic sclerosis in mice (Ccl2 and Adam8)." (PMID 35648793, 2022).
adenoma (1 paper, 2023). A neoplasm arising from the epithelium. "Finally, the expression of the revealed hub genes related to acute colitis (C3, Tyrobp, Mmp3, Mmp9, Timp1) and CAC (Timp1, Adam8, Mmp7, Mmp13) was validated by qRT-PCR in the colon tissue of mice with acute colitis and colitis-driven adenomas." (PMID 36901742, 2023). "Interestingly, despite the proven association with CAC, TIMP1, MMP7, and ADAM8 were activated in IBD-affected colon tissues, which is fully in line with our data: the high expression of these genes was demonstrated in DSS-inflamed and adjacent to adenomas colon tissues in mice." (PMID 36901742, 2023).
alcohol dependence (1 paper, 2021). Physical and psychological dependence on alcohol. "There is currently limited information on the role of Adam8 as it relates to alcohol dependence." (PMID 34573170, 2021).
atopic dermatitis (1 paper, 2020). "To conclude, this study showed that the GCF concentrations of ADAM8, ADAM9, Cathepsin E, MMP8, CD10, Protein convertase 9, and uPA/Urokinase proteases were downregulated in moderate/severe atopic dermatitis patients compared to healthy controls." (PMID 33255937, 2020).
autism (1 paper, 2015). Persistent deficits in social interaction and communication and interaction as well as a markedly restricted repertoire of activity and interest as well as repetitive patterns of behavior. "The ADAM8 gene encodes a protein that is implicated in neurogenesis and muscle development and has been associated with susceptibility to autism." (PMID 26294985, 2015).
autism spectrum disorder (1 paper, 2024). A spectrum of developmental disorders that includes autism, and Asperger syndrome. "A recent study reported that ADAM8 was linked to neuroinflammation-induced autism spectrum disorder in children." (PMID 38755530, 2024).
chronic rhinosinusitis (1 paper, 2024). Chronic form of sinusitis. "A disintegrin and metalloproteinase 8 (ADAM8) has been implicated in eosinophilic inflammation; however, its role in chronic rhinosinusitis with nasal polyps (CRSwNP) remains to be elucidated." (PMID 39588470, 2024).
colitis (1 paper, 2023). Inflammation of the colon. "Given the recently demonstrated ability of Adam8 to control neutrophil transmigration and NLRP3 inflammasome activation, the processes tightly associated with colon inflammation, Adam8 can be considered as a novel promising master regulator of colitis and CAC; this requires further clarification." (PMID 36901742, 2023). "All explored hub genes, except for Adam8, indeed form tight modules with gene partners within the evaluated regulomes, and are related to diverse processes and signaling pathways important for the pathogenesis of colitis and CAC." (PMID 36901742, 2023).
delirium (1 paper, 2026). A disorder characterized by confusion; inattentiveness; disorientation; illusions; hallucinations; agitation; and in some instances autonomic nervous system overactivity. "Using delirium in the dementia-free UKB GWAS as outcome, ADAM8, CCL25, PILRA and LAYN lost their MR causal effect significance (FDR q > 0.05)." (PMID 41286463, 2026).
dermatitis (1 paper, 2025). An inflammatory process affecting the skin. "Transcriptomic analysis and machine-learning models enable patient stratification, allowing for the identification of biomarkers such as ADAM8, CD47, BATF, SELE, IL-37 that may aid in diagnosis and differentiating ACD from other forms of dermatitis." (PMID 40181807, 2025).
diabetes (1 paper, 2018). "Our data justify the anti-inflammatory properties of metformin independently of diabetes status and suggest the potential contribution of ADAM8 in the process." (PMID 30545422, 2018).
head and neck squamous cell carcinoma (1 paper, 2012). A squamous cell carcinoma that arises from any of the following anatomic sites: lip and oral cavity, nasal cavity, paranasal sinuses, pharynx, larynx, and salivary glands. "In the prospective study we analyzed the utility of ADAM8 as a diagnostic and prognostic tool in patients with head and neck squamous cell carcinomas." (PMID 22369429, 2012). "In summary ADAM8 expression is a prognostic factor for survival of patients with head and neck squamous cell carcinoma." (PMID 22369429, 2012).
hepatitis (1 paper, 2021). Inflammation of the liver. "Here, we report that the induction of inflammatory mediators is associated with a yet undescribed upregulation of the metalloproteinase ADAM8 in different murine hepatitis models." (PMID 33814981, 2021).
infarction (1 paper, 2022). A localised pathological necrosis of tissue resulting from obstruction of the blood supply usually by a thrombus, an embolus, or vascular torsion. "The markers LPL, M-CSF, and ADAM8 were also consistently expressed by F4/80+ cells within the infarction core." (PMID 35177618, 2022). "Also, the density of LPL+, M-CSF+, and ADAM8+ cells increased and spread from the infarction core to the cerebral cortex, confirming expression of the top SAMC markers in ischemic brain parenchyma." (PMID 35177618, 2022).
kidney cancer (1 paper, 2023). Primary or metastatic malignant neoplasm involving the kidney. "Increased expression of Adam8 has been correlated with enhanced tumor growth and metastasis in breast, brain, pancreatic, liver, colon, and kidney cancers." (PMID 37370863, 2023). "Increased expression of Adam8 has been correlated with enhanced tumor growth and metastasis in breast, pancreatic, liver, colon, and kidney cancers, among others." (PMID 37370863, 2023).
leukemia (1 paper, 2024). A malignant (clonal) hematologic disorder, involving hematopoietic stem cells and characterized by the presence of primitive or atypical myeloid or lymphoid cells in the bone marrow and the blood. "CD74, TNFRSF1B, and ADAM8 all have important roles in the immune system and have enrichment for mRNA expression on candidate cells of origin for NHL and leukaemia." (PMID 38750076, 2024).
liver fibrosis (1 paper, 2024). "Compared with the alcohol group, ADAM8 mRNA, protein and, positive area rate, serological indicators, pathological changes, and the expression of liver fibrosis marker and MAPK signaling pathway-related factors in the ADAM8-sgRNA3 plasmid group significantly decreased in vivo." (PMID 39407108, 2024). "Compared with the alcohol group, ADAM8 mRNA and protein expression, cell viability, and the expression of liver fibrosis markers and MAPK signaling pathway-related factors (p-ERK1/2, PCNA, Bcl-2, p-c-Jun, TGFβ1, p–p38 MAPK and HSP27) reduced significantly in the si-ADAM8-2 group." (PMID 39407108, 2024). "This suggests that ADAM8 may be a potential biomarker in the development of liver fibrosis." (PMID 39407108, 2024). "In the present study, the expression of ADAM8 and MAPK signaling pathway-related factors was higher during alcohol-induced liver fibrosis." (PMID 39407108, 2024).
liver inflammation (1 paper, 2021). "Here, we report the yet undescribed upregulation of ADAM8 in different murine models of LPS or high-fat-induced liver inflammation and its importance for the production of inflammatory mediators in different types of cultured murine and human liver cells." (PMID 33814981, 2021). "Here, we demonstrate that the induction of inflammatory mediators during acute and chronic liver inflammation is correlated with an increased expression of ADAM8." (PMID 33814981, 2021). "Thus, ADAM8 is upregulated in acute and chronic liver inflammation and is able to promote inflammation by enhancing expression and release of inflammatory mediators." (PMID 33814981, 2021). "Also in chronic models of liver inflammation including nonalcoholic steatohepatitis, we observed increased ADAM8 expression." (PMID 33814981, 2021). "However, ADAM8 has not been yet studied in the context of acute and chronic liver inflammation." (PMID 33814981, 2021).
nasal polyps (1 paper, 2024). "In comparison to the HC group, both the eCRSwNP and neCRSwNP groups exhibited significantly elevated levels of ADAM8 in nasal polyp tissues, with eCRSwNP demonstrating higher levels than neCRSwNP." (PMID 39588470, 2024). "In comparison to the HC group, both the uncontrolled and controlled CRSwNP groups exhibited significantly elevated levels of ADAM8 in nasal polyp tissues, with the uncontrolled CRSwNP group demonstrating higher levels than the controlled group." (PMID 39588470, 2024). "Integrating previous observations with the findings of the present study, we hypothesize that the overproduction of ADAM8 in nasal polyps may facilitate its infiltration into the extracellular space in a soluble form." (PMID 39588470, 2024).
polyp (1 paper, 2024). A usually exophytic mass attached to the underlying tissue by a broad base or a thin stalk. "Ultimately, an increase in local ADAM8 concentration may exacerbate eosinophilic inflammation in polyp tissue." (PMID 39588470, 2024).
prostate carcinoma (1 paper, 2024). A carcinoma that arises from epithelial cells of the prostate gland. "Consistent with the influence on proliferation signaling in MM observed herein, ADAM8, 9 and 15 have been shown to influence the proliferation of e.g. hepatocellular, renal and prostate cancer." (PMID 39261477, 2024).
renal carcinoma (1 paper, 2021). A carcinoma arising from the epithelium of the renal parenchyma or the renal pelvis. "The results showed that EIF4EBP1, FOXM1, PLG, and VWF were highly expressed in renal carcinoma compared with normal renal tissue, and ADAM8, CGN, G6PC, ITIH4, and MMP3 were low in expression in renal carcinoma compared with normal renal tissue." (PMID 33968297, 2021).
renal clear cell carcinoma (1 paper, 2024). "Lastly, ADAM8 knockdown renal clear cell carcinoma inhibited tumor formation and increased the survival of mice." (PMID 39329961, 2024).
rheumatic diseases (1 paper, 2024). "Regarding ADAM8 expression, it has primarily focused on cancer, rheumatic diseases, and respiratory diseases, with neutrophils and eosinophils being the main immune cell populations studied." (PMID 39100683, 2024).
squamous cell carcinomas of the lung (1 paper, 2012). "ADAM8 has been found to be overexpressed in squamous cell carcinomas of the lung." (PMID 22369429, 2012).
synovitis (1 paper, 2024). Inflammation of a synovial membrane. "Our study indicates that the ADAM8/FSCN1/MAPK signaling axis may play a crucial role in the progression of OA-related synovitis." (PMID 38218854, 2024).
ventilator-associated pneumonia (1 paper, 2025). Serious INFLAMMATION of the LUNG in patients who required the use of PULMONARY VENTILATOR. "In ventilator-associated pneumonia (VAP), distinct gene expression profiles have been identified, showing downregulation of genes like PIK3R3, ATP2A1, PI3, ADAM8, and HCN4." (PMID 39941194, 2025).
tumor (61 papers, 2010 to 2026). "In prostate cancer, ADAM8 expression was significantly associated with higher tumour stages, nodal involvement, and Gleason scores, although its value in predicting relapse-free survival was limited." (PMID 40427200, 2025). "Given this correlation, the effects of ADAM8 deficiency or miR-181a-5p overexpression on tumor suppression were similar." (PMID 39412616, 2025). "Most recently, a more systematic dissection of tumor-associated immune cells in cancer tissue derived from PDAC patients identified that ADAM8 is also expressed in macrophages, neutrophils, and NK cells." (PMID 36910158, 2023). "Since ADAM8 expression is induced in responding tumors and PD-L1 shedding is likely to decrease the anti-tumor activities of T-cells, we conclude that immunotherapy resistance is caused, at least in part, by the increased presence of proteases, such as ADAM8." (PMID 38139457, 2023). "Recently, a systematic analysis of tumor-associated immune cells in tumor tissues of PDAC patients revealed the additional expression of ADAM8 in macrophages, neutrophils, and NK cells." (PMID 35216088, 2022). "Studies have shown that ADAM8 is highly expressed in a variety of malignant tumours and is strongly associated with tumour metastasis and poor patient prognosis." (PMID 35860566, 2022). "Herein, we revealed a novel concept of an intra-tumoral ADAM8 mediated malignant positive feedback loop constituted by the intimate interaction of tumor associated macrophages (TAMs) and GBM cells under TMZ treatment." (PMID 36230833, 2022). "ADAM8, a metalloprotease-disintegrin strongly expressed in tumor cells and associated immune cells of GBMs is related to angiogenesis and is correlated with poor clinical prognosis." (PMID 35600367, 2022). "High expression of ADAM8 in tumor cells has been shown to be associated with invasion and metastasis of cancer cells and is associated with poor prognosis in patients." (PMID 33968297, 2021). "In previous studies, ADAM8 was defined as an ADAM protease associated with tumor progression and metastasis formation in PDAC." (PMID 34368146, 2021). "JG26 and compounds 1–3 were finallytested fortheir capacity to affect the invasive potential of tumor cells, aneffect that, at least in part, is dependent on the ADAM8 proteolyticactivity, as ADAM8-deficient cell lines suggest." (PMID 35111280, 2021). "Of note, these signalling processes were all found to be dependent on ADAM8 expression, underlining that ADAM8 is an essential factor in tumour cells." (PMID 33314720, 2021). "The pro-tumorigenic effect of ADAM8 was linked to its association with β1-integrin and the resulting increase in tumour cell motility, invasiveness and activation of the MAP kinases ERK1/2." (PMID 32698506, 2020). "As seen in the Kaplan Meier curve strong ADAM8 staining in the tumor is associated with worse survival rates." (PMID 22369429, 2012). "ADAM8 deficiency has previously been associated with reduced migration of tumor cells and several types of immune cells." (PMID 20856819, 2010). "Tumors with KRAS 12/13 mutations may exhibit a more aggressive tumor phenotype potentially due to the significant association of ADAM8 with the formation of distant metastases and the invasion of the tumor environment." (PMID 39329961, 2024). "In tumor mice with an overall therapy response, expression of genes encoding the proteases ADAM8, ADAM10, and ADAM17 was increased and might contribute to the immunosuppressive phenotype of GB and immune cells." (PMID 38139457, 2023). "In addition, ADAM8 is expressed in tumor associated immune cells such as macrophages, NK cells and neutrophils." (PMID 34368146, 2021). "ADAM8 has functionally been associated with tumor and immune cell migration." (PMID 20856819, 2010).